ALK (ALK receptor tyrosine kinase)
Diseases named in the same sentence as ALK in open-access papers (continued):
Sharing a sentence is not in itself a finding about the gene and the disease.
brain tumors (13 papers, 2017 to 2024). "Patient #1 with medulloblastoma and ALK germline variant had a cousin with a brain tumor in childhood." (PMID 38139220, 2023). "gDNA extracted from the brain tumor biopsy was sequenced and G1202R ALK mutation was found (variant allele frequency 26.5%)." (PMID 30453899, 2018). "Findings suggest that examining ALK can help in diagnosing and predicting the outcome of some of these brain tumors, especially medulloblastoma." (PMID 38339401, 2024). "We have confirmed ALK rearrangement positivity in the primary lung tumor and all metastatic sites except for metastatic bone and brain tumors." (PMID 33352665, 2020). "This potential is particularly intriguing for Lorlatinib, whose design specifically targets CNS activity and might offer substantial therapeutic benefits in primary brain tumors with ALK involvement." (PMID 38339401, 2024). "Then, we review the previous literature using PubMed on maternal malignant brain tumors diagnosed during pregnancy, or lung LCNEC associated with ALK fusion, or ALK inhibitors treatment among the pregnant women, eventually, and discuss the concerns of dealing with these patients." (PMID 35280726, 2022). "Although the current patient with ALK rearrangement-positive LCNEC received ALK-TKI, alectinib and achieved a PR for 11 months, the brain tumor had acquired resistance to ALK-TKI similar to a case previously reported." (PMID 33352665, 2020). "A review of scientific studies was conducted to understand ALK’s role in certain brain tumors, particularly those not originating from glial cells (supportive cells in the brain) and located in the lower back part of the brain." (PMID 38339401, 2024). "Brain tumor regression was observed in mice receiving alectinib and in ALK-positive NSCLC patients not previously treated with brain radiotherapy." (PMID 30052658, 2018).
Burkitt lymphoma (13 papers, 2016 to 2025). A rare form of malignant mature B-cell non-Hodgkin lymphoma. "Other exceedingly rare differential diagnoses include intravascular DLBCL, plasmablastic lymphoma, anaplastic lymphoma kinase (ALK)-positive large BCL, and Burkitt lymphoma." (PMID 40227781, 2025). "The established PDX models comprised all major aggressive NHL subtypes, including DLBCL of the germinal center (GC) and non-GC immunophenotypes, double-hit DLBCL, transformed DLBCL, MCL, Burkitt lymphoma, PTCL, AITL, ALCL, ALK-positive, and ALCL, ALK-negative." (PMID 35488033, 2022).
cervical carcinoma (13 papers, 2010 to 2025). A carcinoma arising from either the exocervical squamous epithelium or the endocervical glandular epithelium. "Crizotinib, an inhibitor of mesenchymal epithelial transforming factor (c-MET) and anaplastic lymphoma kinase (ALK), has shown promising anticancer effects in cervical cancer." (PMID 36561319, 2022). "Trop2 also exhibits tumor suppressive functions in cervical cancer cells, where it similarly inhibits the activation of IGF-1R and anaplastic lymphoma kinase (ALK), possibly through binding to their ligands IGF-1 and midkine (MDK)." (PMID 33187148, 2020). "ALK, PHOX2B and PHOX2A resulted to be highly expressed in almost all analyzed NB cell lines with respect to a pool of normal tissues and to HeLa cells, a cervix carcinoma cell line characterized by low level of ALK expression and almost undetectable expression levels of the two PHOX2 genes." (PMID 20957039, 2010).
non-squamous non-small cell lung cancer (13 papers, 2018 to 2025). "In 2015, guidelines recommended the evaluation of only two molecular markers: epidermal growth factor receptor (EGFR) mutations and anaplastic lymphoma kinase (ALK) fusions, in patients with non-squamous non-small cell lung cancer." (PMID 39064008, 2024). "In non-small cell, non-squamous lung cancer, endothelial growth factor receptor (EGFR) mutations are present in 20 % and anaplastic lymphoma kinase (ALK) rearrangements are present in 3–5 % of cases." (PMID 41541744, 2025). "In the same year, it was designated by the FDA as a breakthrough therapy for metastatic squamous and non-squamous non-small cell lung cancer (NSCLC) with PD-L1 expression which continued to progress on or after platinum-based chemotherapy or an FDA-approved EGFR or ALK targeted agent." (PMID 39974747, 2025). "In non-squamous non-small-cell lung cancer, 9/15 were all EGFR, ALK, and ROS1 wild-type." (PMID 33042826, 2020).
renal carcinoma (13 papers, 2012 to 2025). A carcinoma arising from the epithelium of the renal parenchyma or the renal pelvis. "RCC associated with anaplastic lymphoma kinase (ALK) gene rearrangements (ALK-RCC) is a novel renal cancer entity, currently considered as “emerging or provisional”." (PMID 35409355, 2022). "Similarly, STRN mutations can generate STRN/ALK fusion proteins, previously linked to metastatic progression in colorectal, breast, and renal cancers." (PMID 40486961, 2025). "The molecularly defined renal carcinomas include TFE3-rearranged RCC, TFEB-altered RCC, ELOC-mutated RCC, FH-deficient and SDH-deficient RCC, ALK-rearranged RCC, and SMARCB1-deficient renal medullary carcinomas." (PMID 38235567, 2024). "In this light, a consensus paper would be useful to provide recommendations for a test algorithm for renal cancer and the quality of the respective test approaches, like the one released regarding ALK testing in NSCLC." (PMID 35409355, 2022). "As another member of the JADE family JADE1 has been linked to renal cancer pathogenesis through a VHL-mutation-dependent mechanism, we next sought to determine if JADE2 mRNA was also associated with mutation of key oncogenic driver mutations in NSCLC such as KRAS or ALK." (PMID 37761019, 2023). "No liquid biopsy data on other ALK+ cancer types, such as renal carcinoma, have been found in our literature search." (PMID 34680298, 2021).
Sepsis (13 papers, 2019 to 2024). Sepsis is defined as life-threatening organ dysfunction caused by a dysregulated host response to infection. "However, only a small part of MVPs have relatively large Δβ (|Δβ|> 0.2), and focusing on those with large Δβ, we found that 6 of 26 differentially methylated genes (23.1%) were previously associated with sepsis in the literature, including ALK, ZEB2, MNDA, AIM2, TLR5, and JUNB." (PMID 35242787, 2022). "The novel ALK-EGFR-AKT pathway has recently been proposed as a therapeutic target for sepsis research." (PMID 37109229, 2023). "During sepsis, ALK expression in monocytes and macrophages is upregulated, and genetic and pharmacological inhibition of ALK or STING have both corrected hyperinflammation and improved survival in mice." (PMID 37109229, 2023). "This study was carried out to study the crosstalk between GAS5 and miR-146a in sepsis-induced acute lung injury (sepsis-ALK)." (PMID 35112981, 2022). "Subsequent gene silencing of ALK in immortalized mice bone marrow–derived macrophages (iBMDMs) confirmed ALK’s role in STING activation during sepsis." (PMID 32059449, 2020). "This ALK-STING axis is later found to be involved in cecal ligation and puncture-induced sepsis in rat models, in which ceritinib-mediated inhibition of ALK significantly reduced sepsis-induced organ injuries and deaths of these septic rats." (PMID 32059449, 2020). "LDK378, a second-generation ALK inhibitor, exhibits a potential anti-inflammatory function against sepsis." (PMID 30820191, 2019). "Moreover, the decreases in the expression levels of GAS5 and miR-146a were higher in sepsis-ALK patients in comparison to that in sepsis patients." (PMID 35112981, 2022). "GAS5 and miR-146a were downregulated in sepsis-ALK and GAS5 may decrease miR-146a gene methylation to upregulate miR-146a, thereby decreasing the apoptosis of HBEpCs induced by LPS." (PMID 35112981, 2022). "Since anaplastic lymphoma kinase (ALK) activates STING during sepsis, it is expected that clinically used ALK inhibitors (e.g., ceritinib) might block GSDMD activation in macrophages." (PMID 36209190, 2022). "Our data illustrated that GAS5 and miR-146a were both downregulated in sepsis-ALK." (PMID 35112981, 2022). "The crosstalk between GAS5 and miR-146a in sepsis-ALK was investigated." (PMID 35112981, 2022). "Activation of the STING pathway by ALK may be a crucial step for its immunological activity and may contribute to the pathogenesis of sepsis." (PMID 30820191, 2019). "Therefore, GAS5 and miR-146a may serve as potential targets to improve the conditions of sepsis-ALK patients." (PMID 35112981, 2022). "Therefore, the reduction of GAS5 and miR-146a in lung tissues of sepsis-ALK patients may significantly affect their expression levels in plasma." (PMID 35112981, 2022). "However, we observed the significant correlation between GAS5 and miR-146a only across sepsis-ALK." (PMID 35112981, 2022). "Furthermore, the ALK KO mice were more resistant to polymicrobial sepsis." (PMID 34638546, 2021). "A previous study showed that anaplastic lymphoma kinase (ALK), a DAMP, crucially participates in the regulation of the innate immune response after sepsis." (PMID 36445634, 2023). "Thus, ALK may represent a potential therapeutic target for lethal sepsis." (PMID 32059449, 2020). "A previous study found that both STING-KO mice and TRIF-KO mice were protected from sepsis in a severe CLP model, and the ALK-STING pathway was upregulated more in a human sepsis group than a control group." (PMID 30820191, 2019). "LDK378, a novel ALK inhibitor approved for advanced-stage non-small cell lung cancer (NSCLC) with ALK gene rearrangement, exhibited promising anti-inflammatory activity in animal models of lethal sepsis." (PMID 30820191, 2019). "Interestingly, we showed that GAS5 and miR-146a were downregulated in both sepsis patients without obvious complications and sepsis-ALK patients." (PMID 35112981, 2022).
T-cell neoplasms (13 papers, 2013 to 2024). "According to the 2008 version of the WHO classification, ALK+ ALCL is a rare type of mature T cell neoplasm." (PMID 28490385, 2017). "We selected representative genes by merging the RNA sequencing expression data available in the literature and identified a group of genes that were differentially expressed between BIA-ALCL and at least three different T-cell neoplasm entities (e.g., ALCL, AITL, ALK-ALCL, ALK+ ALCL, and PTCL-NOS)." (PMID 32560455, 2020). "Systemic anaplastic large-cell lymphoma (ALCL) is a childhood T cell neoplasm defined by the presence or absence of translocations that lead to the ectopic expression of anaplastic lymphoma kinase (ALK), with nucleophosmin-ALK (NPM-ALK) fusions being the most common." (PMID 29581862, 2018). "As defined by the WHO in 2017, ALK- ALCL is a “CD30+ T-cell neoplasm that is not reproducibly distinguishable on morphologic grounds from ALK+ ALCL, but lacks (ALK) protein expression”." (PMID 34572893, 2021). "As currently defined, ALCL, ALK negative comprises CD30(+) T-cell neoplasms that are not reproducibly distinguishable on morphological grounds from ALCL, ALK positive." (PMID 25143841, 2014).
childhood cancer (12 papers, 2010 to 2024). "The childhood cancer NB, is a heterogeneous disease that exhibits ALK mutations in up to 10% of primary NB, and at higher levels on relapse." (PMID 38858548, 2024). "Personalized medicine in childhood cancer aims for the identification of actionable alterations and some promising molecular drug targets are already being translated into clinical applications (e.g., ALK, NTRK, MET, BRAF)." (PMID 35159116, 2022). "Abnormalities in six genes (NRAS, ABL1, JAK2, KIT, ALK and BRAF) were common in childhood cancers as well as adult cancers, for which at least one approved drug could be a potentially actionable drug." (PMID 33051474, 2020).
enteropathy-associated T-cell lymphoma (12 papers, 2018 to 2025). An uncommon mature T-cell lymphoma of intraepithelial lymphocytes. "Our study enrolled more histologic subtypes (including ALK+ALCL, Enteropathy-associated T-cell lymphoma (EATL), and others); the differences between the study populations in the two studies may be one of the reasons for the contrary results." (PMID 36465366, 2022).
large cell neuroendocrine carcinoma (12 papers, 2019 to 2025). A usually aggressive carcinoma composed of large malignant cells which display neuroendocrine characteristics. "A 58-year-old female patient (case NCCLu-237) was diagnosed with stage IV large-cell neuroendocrine carcinoma displaying ALK fusion." (PMID 38398169, 2024). "Case #4, with large cell neuroendocrine carcinoma histology, exhibited a mild and peculiar reactivity not characteristic of the conventional expression pattern resulting from ALK rearrangement." (PMID 36612287, 2022). "Few case reports described the occurrence of such rearrangements in large cell neuroendocrine carcinomas (LCNECs) of the lung without information on clinical responses to ALK tyrosine kinase inhibitors (TKIs) in these cases." (PMID 35756632, 2022). "Significant ALK IHC staining of E5193 was established on 100 cells only (25% of tumor cells in the sample) and patient E5680 was an active smoker with large cell neuroendocrine carcinoma, not prone to present ALK rearrangement." (PMID 31651105, 2019).
mesothelioma (12 papers, 2016 to 2026). A usually malignant and aggressive neoplasm of the mesothelium which is often associated with exposure to asbestos. "Although anaplastic lymphoma kinase gene (ALK) double-fusion partners have been found in various tumors, it is rarely reported in mesothelioma." (PMID 37152028, 2023). "Rare cases of mesothelioma have been described with mutations in KRAS, NRAS and potential oncogenic fusions involving ALK and EWSR1 rearrangements, as well as inactivating mutations in VHL raising the possibility of targeted therapy in such cases." (PMID 38015374, 2023). "In this series of peritoneal mesotheliomas, the authors identified ALK-positive mesotheliomas by immunohistochemistry and confirmed ALK rearrangement by FISH (fluorescence in situ hybridization)." (PMID 36556334, 2022). "To assess the frequency of co-activation in primary mesotheliomas, we examined the co-expression of mTOR and ALK, ROS1, and MET at both mRNA and protein levels in tumor samples by qRT-PCR and IHC, respectively." (PMID 29755689, 2018). "Taken together, rapamycin/crizotinib co-treatment affected aberrant cell signaling in an mTOR/ALK-positive mesothelioma graft by simultaneous blocking of mTORC1, AKT and STAT3." (PMID 29755689, 2018). "We also found that the combined use of rapamycin and crizotinib was more effective than rapamycin as single-agent in suppressing tumor growth in a patient-derived mesothelioma graft with co-activated ALK and mTOR pathways." (PMID 29755689, 2018). "Here, we have explored the anti-tumor effects of a simultaneous inhibition of mTOR and ALK on the growth of a patient-derived mesothelioma graft with co-activated mTOR and ALK." (PMID 29755689, 2018). "Nevertheless, it is worth noting that ALK gene rearrangement and EWSR1/FUS-ATF1 fusion have been reported in young MPM patients, and there is even speculation that ALK fusion-positive mesothelioma tends to predominate in children, women, and abdominal cancers." (PMID 41179684, 2025). "ALK qRT-PCR was applied to 128 mesotheliomas and five normal pleura specimens." (PMID 29755689, 2018). "Therefore, it is tempting to speculate that upregulated ALK expression in mesothelioma might be of therapeutic relevance." (PMID 29755689, 2018). "The UMAP projection showed that all ALK, NR4A3, and MAP3K8-rearranged EM formed distinct subgroups, with transcriptomic similarities based on the histology and the site of mesothelioma." (PMID 39059063, 2024). "In three cases of mesothelioma, in two where the differential diagnosis was of synovial sarcoma, SS18-SSX1/2 molecular analysis was performed, and in one case FISH for ALK gene rearrangement was performed to exclude IMT." (PMID 33061792, 2020). "Here, we studied the combinatorial therapeutic efficacy of the MET/ALK inhibitor crizotinib, with either a pan-class I PI3K inhibitor, BKM120, or with a PI3K/mTOR dual inhibitor, GDC-0980, in mesothelioma." (PMID 27623107, 2016). "Immunostaining of ALK, MET and mTOR on tissue microarrays was interpretable in 101 mesotheliomas." (PMID 29755689, 2018).
mucinous adenocarcinoma (12 papers, 2014 to 2025). An invasive adenocarcinoma composed of malignant glandular cells which contain intracytoplasmic mucin. "Previous studies found that the rate of mutation in the ALK gene in mucinous adenocarcinoma was higher than that of other types of adenocarcinoma, and our study found a higher rate of mutation in the ALK gene in tall column‐like tumour cells." (PMID 38616354, 2024). "ALK rearrangement was significantly associated with younger age, and with the solid predominant with mucin production and invasive mucinous adenocarcinoma subtypes." (PMID 29156778, 2017). "ALK-positivity more frequently occurred in tumours with a solid predominant subtype or in mucinous adenocarcinoma (p < 0.001)." (PMID 32690092, 2020). "ALK positive lung adenocarcinomas often exhibit mucinous features, although these are usually morphologically distinct from classic mucinous adenocarcinoma." (PMID 29515761, 2018). "Previous studies reported that ALK rearrangements were common in signet cell carcinoma and mucinous adenocarcinoma." (PMID 24992725, 2014). "Moreover, in the subtypes of invasive non-mucinous adenocarcinoma, the frequency of ALK translocations was significantly higher in patients with solid-predominant adenocarcinoma than in the other three subtypes of IA." (PMID 39364008, 2024). "This imaging finding was consistent with the correlation between solid lesions on CT and solid-predominant subtypes or mucinous adenocarcinoma in the present study, whereas ALK positivity commonly occurred in tumours of solid-predominant subtypes or mucus patterns." (PMID 33707479, 2021). "Similarly, our study found that the rate of ALK positivity is higher in the solid predominant subtype or in mucinous adenocarcinoma." (PMID 32690092, 2020). "This can be explained by the pathological results in the present study showing that ALK positivity was related to the solid predominant subtype or mucinous adenocarcinoma, because adenocarcinoma with the solid predominant subtype or mucinous adenocarcinoma hardly presented with GGO on CT." (PMID 32690092, 2020). "In our study, acinar, papillary, and mucinous adenocarcinomas were found in ALK-rearranged cases." (PMID 26253541, 2015). "Thus, the ALK gene is usually used as a marker for the diagnosis of mucinous adenocarcinoma." (PMID 38616354, 2024). "ALK rearrangement was detected just in one non-mucinous adenocarcinoma (data not shown) without coexisting NRG1 fusions." (PMID 29515761, 2018).